SOX10 (SRY-box transcription factor 10)
Diseases named in the same sentence as SOX10 in open-access papers (continued):
Sharing a sentence is not in itself a finding about the gene and the disease.
melanoma (continued). "Interestingly, the discovery of elevated SOX10 levels in vitiligo patients suggests that increased immune mediated lysis of melanoma cells has the potential to increase serum concentrations of SOX10." (PMID 27110718, 2016). "In summary, we could confirm our computational predictions, i.e. SOX5 is inducing and SOX10 is repressing MITF expression in the observed melanoma cells." (PMID 26927636, 2016). "Besides overexpressed in malignant melanoma, SOX10 has also been reported to be expressed in other tumors of neural crest origin, such as neurofibroma." (PMID 27110718, 2016). "Furthermore, hierarchical cluster analysis (average linkage and Euclidean distance) showed that SOX5 and SOX10 expression is sufficient to clearly distinguish melanoma from other cancer types." (PMID 26927636, 2016). "The discovery of SOX10 in the serum of melanoma patients suggest that SOX10 could be included in larger combinatorial biomarker panels." (PMID 27110718, 2016). "Using our established regression model (MILP model) and the defined activity, we found the transcription factors SOX5 and SOX10 with which the model could predict best the gene expression values of MITF in various melanoma cell lines." (PMID 26927636, 2016). "In addition, an activating frameshift or non-sense mutations in SOX10 have been identified in melanoma cells, and MITF and SOX10 have been found mutated in a mutually exclusive manner." (PMID 25433395, 2015). "The role of SOX10 in melanoma metastasis has been reported by several studies." (PMID 26461473, 2015). "Moreover, chromatin immunoprecipitation assays in human melanoma M010817 cells indicated that SOX9 binds to the promoter of SOX10, suggesting a direct regulation of the SOX10 gene by SOX9." (PMID 25629959, 2015). "SOX10 was inversely correlated with the Fbxw7α protein levels in melanoma cells." (PMID 26461473, 2015). "Based on the assumption that mechanisms of tumor formation might be related to those underlying the generation of the cell type, from which the tumor develops, we and others have recently addressed the function of Sox10 in melanoma." (PMID 25629959, 2015). "This study provides evidence that the tumor suppressor Fbxw7α is the E3 ubiquitin ligase responsible for the degradation of SOX10, and suggests that reduced Fbxw7α might contribute to the upregulation of SOX10 in melanoma cells." (PMID 26461473, 2015). "We investigated the role of SOX10 in Fbxw7α-mediated migratory inhibition of melanoma cells." (PMID 26461473, 2015). "Previous studies have revealed low frequencies of intragenic mutations of the Sox10 gene in metastatic melanoma, suggesting that SOX10 might be involved in mediating melanoma metastasis." (PMID 26461473, 2015). "Interestingly, the vast majority of human melanoma samples displayed much higher SOX10 than SOX9 expression and only very few samples were characterized by a SOX9 high / SOX10 low expression pattern." (PMID 25629959, 2015). "Fbxw7α and SOX10 protein levels were detected by Western blotting in a panel of melanoma cells." (PMID 26461473, 2015). "The inactivation of Fbxw7α may lead to the accumulation of SOX10, which promotes melanoma migration." (PMID 26461473, 2015). "To this end, we performed RNAi experiments to test whether interfering with SOX9 overexpression upon SOX10 knockdown could rescue M010817 melanoma cells." (PMID 25629959, 2015). "Moreover, SOX10 knockdown also resulted in upregulation of SOX9 protein levels in human melanoma cells." (PMID 25629959, 2015). "Moreover, the SOX10 protein level was inversely correlated with Fbxw7α in a panel of melanoma cells." (PMID 26461473, 2015). "Furthermore, upon experimental elevation of SOX9 levels, SOX10 activity is suppressed, revealing an antagonistic relationship between SOX9 and SOX10 in melanoma initiation." (PMID 25629959, 2015).
melanoma (continued). "To address whether changes in PAX3 or SOX10 levels might be responsible for the effect of IL-1ß, we performed quantitative RT-PCR and Western Blot analyzes in several melanoma cell lines." (PMID 25853464, 2015). "An alternative approach to improve detection may be the use of an antibody against SOX10, which has shown superior sensitivity and specificity over the melanoma cocktail." (PMID 26500776, 2015). "Moreover, SOX10 protein levels were inversely correlated with Fbxw7α in melanoma cells, and modulation of Fbxw7α levels regulated the expression of SOX10 and its downstream gene MIA." (PMID 26461473, 2015). "However, the precise molecular mechanisms mediating Sox10 function in melanoma remain to be investigated." (PMID 25629959, 2015). "To functionally assess the role of SoxE factors in melanomagenesis, we first performed immunohistochemical staining for Sox9 and Sox10 of giant congenital naevi formed in Tyr::NrasQ61K mice and in melanoma derived from giant congenital naevi in Tyr::NrasQ61KInk4a−/− mice." (PMID 25629959, 2015). "To determine whether the SOX10 protein is stable, we assessed the half-life of SOX10 in melanoma cells using the cycloheximide (CHX) chase assay." (PMID 26461473, 2015). "Therefore, SOX-10 cannot be used to differentiate melanoma from benign melanocytic tissue in ocular specimens." (PMID 26316887, 2015). "To address this hypothesis, we overexpressed SOX9 in human M010817 melanoma cells in vitro and compared the gene expression profile of these cells with that of SOX10 knock-down melanoma cells, using the parental M010817 cell line as control." (PMID 25629959, 2015). "In this study, we found that Fbxw7α promoted SOX10 degradation in melanoma cells." (PMID 26461473, 2015). "Furthermore, Fbxw7α-mediated degradation of SOX10 is pathologically relevant, given that SOX10 can reverse the Fbxw7α-mediated migration-suppression effect on melanoma cells." (PMID 26461473, 2015). "While this further emphasizes the close connection of the MAPK pathway with the regulation of MITF in melanoma cells, the role of SOX10 and FOXD3 in regulating MITF downstream of ERK under physiological conditions in melanocytes is so far unknown." (PMID 25818589, 2015). "More importantly, SOX10 reversed Fbxw7α-mediated suppression of melanoma cell migration." (PMID 26461473, 2015). "However, Sox9 expression is elevated upon Sox10 deletion in mouse and human melanoma cells, and critically contributes to the anti-tumorigenic effects observed upon Sox10 inactivation in giant congenital naevus and melanoma." (PMID 25629959, 2015). "Likewise, all samples of a melanoma tissue microarray composed of 56 primary melanoma biopsies revealed strong SOX10 expression." (PMID 25629959, 2015). "Given the frequent downregulation or inactivation of Fbxw7α in melanoma, these findings may help us further understand the roles of the Fbxw7α-SOX10 axis in melanoma progression." (PMID 26461473, 2015). "In melanomas, upregulation of SOX10 correlates well with promoter hypomethylation." (PMID 25301735, 2014). "In human patients, virtually all congenital nevi and melanomas are SOX10 positive." (PMID 24743024, 2014). "The role of SOX10 in regulating EGFR in melanoma was further supported by the discovery of an inverse relationship between SOX10 and EGFR gene expression in a panel of BRAF mutant melanoma cell lines, as well as in a few BRAF mutant melanoma patient samples following treatment-associated resistance." (PMID 25031620, 2014). "SOX10 expression was first examined in 16 melanomas in a tissue microarray." (PMID 25301735, 2014). "Although emerging evidences together with ours support that SOX10 functions as a tumor suppressor in certain tumors, overexpression and oncogenic property of SOX10 have been reported in melanoma and glioma, indicating that SOX10 plays a complex role in tumorigenesis." (PMID 25301735, 2014).
melanoma (continued). "We elucidated whether the level of SOX10 in melanoma cells changed by treatment with TGFβ2 and concomitantly led to expression of CD133." (PMID 24799129, 2014). "Our findings confirm previous observations regarding the role of CD271 and SOX10 in melanoma cells." (PMID 24799129, 2014). "SOX10 has been implicated in migration and metastasis of B16F10 mouse melanoma cells." (PMID 24098529, 2013). "In human patients, virtually all congenital nevi and melanomas have upregulated SOX10 expression." (PMID 23576382, 2013). "We show that B16F10 melanoma cells transfected with siRNAs specific for Sox10 display reduced migratory activity which in turn indicated that a subset of transcriptional regulatory target genes of Sox10 is likely to be involved in migration and metastasis of melanoma cells." (PMID 22363655, 2012). "It should be noted that whether the Sox10-Mitf axis is functional in regulating migratory behavior of all melanoma is questionable at this stage." (PMID 22363655, 2012). "Sox10-Mitf axis may be co-opted for different roles in different melanoma cells, and it may thus be possible or even necessary to group melanomas into distinct sets based on the role of Sox10-Mitf axis." (PMID 22363655, 2012). "We thus define multiple potential effectors of migration downstream to Sox10 in melanoma cells." (PMID 22363655, 2012). "MITF and SOX10 mRNA levels in melanocytes and melanoma cell lines following ATF2 KD." (PMID 21203491, 2010). "To further assess whether ATF2 regulation of MITF is SOX10-dependent in melanocytes and melanoma cells, we coexpressed SOX10 in shATF2-expressing cells." (PMID 21203491, 2010). "Similarly, inhibition of ATF2 transcription in human melanoma 1361 cells increased SOX10 and FOXD3 transcription, albeit, to a lesser degree (3- and 1.5-fold, respectively) compared with human melanocytes." (PMID 21203491, 2010). "Notably, the melanocytes and 2/4 melanoma cell lines revealed ATF2 effect on MITF expression is SOX10-dependent (WM1361, WM793)." (PMID 21203491, 2010). "Notably, about 4/12 melanoma lines revealed increase in both SOX10 and MITF expression upon KD of ATF2." (PMID 21203491, 2010). "Furthermore, we identified that the transcription factor SOX10, which is critical for melanocyte development, was specifically highly expressed in melanoma and directly upregulated ACAT2 expression, thereby promoting cholesterol synthesis and tumor proliferation." (PMID 41694582, 2026). "Therefore, understanding SOX10's role in melanoma could lead to novel therapies, particularly in reducing stemness properties that drive malignant transformation." (PMID 40458894, 2025). "To identify and study miRNA‐mediated motifs, we used a systems biology approach, in which we reconstructed a SOX10 network, identified miRNA‐mediated network motifs, analyzed the gene expression dynamics in those motifs, and provided them biomedical explanations related to melanoma." (PMID 40458894, 2025). "Similarly, SOX10 is positive in melanoma and some soft tissue tumors." (PMID 40025593, 2025). "Additionally, the role of SOX10 in melanoma drug resistance has been explored." (PMID 40342816, 2025). "Another observed state is the undifferentiated phenotype, marked by low levels of SOX10 (SRY-related HMG-box 10) transcription factor and elevated expression of tyrosine kinases such as AXL and EGFR, associated with aggressive and drug-resistant melanoma subtypes." (PMID 40872623, 2025). "Similarly, SOX10 deletion inhibited the growth of melanoma cell lines in vivo." (PMID 40342816, 2025). "Indeed, the expression dynamics of SOX10 and KIT during melanoma progression reveal an intriguing pattern: SOX10 expression gradually increases throughout disease progression, whereas KIT shows biphasic regulation—upregulated in primary melanoma but subsequently downregulated during metastasis." (PMID 40458894, 2025).
melanoma (continued). "As A-485 was found to induce degradation of SOX10 protein levels without associated changes in SOX10 transcription, we sought to determine the broader transcriptional consequences of A-485 on melanoma cells and to assess the expression of the global SOX10 gene network." (PMID 38994683, 2024). "Additionally, through transcriptome profiling of 11 melanoma cell lines, we found the presence of ATP1A1 in the Verfaillie proliferative gene signature, which is associated with the melanocytic state characterized by MITF and SOX10 expression." (PMID 38178183, 2024). "SOX10 could regulate melanoma growth via PI3K/Akt pathway activation." (PMID 37484916, 2023). "Loss of SOX10 in melanoma cells results in cell cycle arrest in the G1 phase, accompanied by molecular changes such as reduced MITF expression, elevated p21/WAF1 and p27KIP2 expression, hypo-phosphorylated RB, and reduced levels of E2F1; SOX10 is essential for melanogenesis." (PMID 38132479, 2023). "Moreover, the GSK-3β-dependent Wnt pathway activation appears to reduce invasion and proliferation of melanoma cells in vitro and melanoma growth in xenografts in vivo by suppressing the expression of Sox10, which significantly increased in our nevi and melanoma samples." (PMID 38020918, 2023). "However, it is unknown whether curcumin affects the expression of miR-222-3p and SOX10, and whether there is interaction between miR-222-3p and SOX10 in melanoma." (PMID 35585935, 2022). "Melanomas display immunostaining characteristics of melanocytic differentiation such as protein melan-A (MelanA) or MART1, microphtalmia-associated transcription factor (MITF), Human Melanoma Black (HMB45), SRY-related HMG-box 10 protein (SOX10), and S-100 protein positivity." (PMID 35334544, 2022). "Furthermore, in a study conducted on CD133 + transgenic mice and human melanoma cells, promotion of neovascularisation in tumour microenvironment was induced by the Sox10 high expression, along with that of organic cation transporter (OCT) 3/4 and Nanog homeobox (Nanog)." (PMID 35334544, 2022). "In our previous study, we found that SOX10 mRNA and protein expression was obviously increased in melanoma tissue samples compared to normal tissue samples, which could significantly promote the melanoma cell proliferation via activating Notch pathway." (PMID 35585935, 2022). "Therefore, MITF and SOX10 are melanocyte-specific transcription factors that regulate pigmentation and contribute to protection against UV radiation, but also play significant roles in promoting aspects of melanoma tumorigenicity." (PMID 35323214, 2022). "Moreover, using dot blot assay with antibody against 5-methylcytosine (5-mC), we observed that global methylation was also increased in the SOX10– melanoma cell lines (P = 0.0003), suggesting a global effect on methylation patterns in cells that have lost the expression of SOX10." (PMID 36040798, 2022). "In addition, some normal cells may also display SOX10 positivity, e.g., Schwann cells, cells of eccrine sweat glands, and mast cells that may be very abundant in the periphery of some melanomas." (PMID 36361209, 2022).
melanoma (continued). "Indeed, open chromatin profiling and chIP-seq against the H3K27ac and H3K27me3 reveal an open and active SOX10 promoter in proliferative/differentiated melanoma cells, while the latter promoter displays the H3K27me3 repressive mark in the invasive/undifferentiated melanoma cells." (PMID 35406721, 2022). "Combined with the western blot results, these results suggested that CD271 and SOX10, which have been recognized as indicators of melanoma stemness, were highly expressed in A2058R and OE cells, indicating that PCK1 could modify cancer stemness in the development of drug resistance." (PMID 36700470, 2022). "Thus, in a recent study, the generation of SOX10 knockout (SOX10-KO) in MITF methylated melanoma cell has shown that SOX10-KO cells revert to a pre-neural crest state characterized by the downregulation of SOX2, SOX5, SOX8, SNAI2 and increased expression of SOX9." (PMID 36497228, 2022). "We further corroborated the involvement of SOX10 in regulating these pathways using two publicly available datasets containing SOX10 knockdown transcriptome data from A375 cells and 6 different patient-derived melanoma cell lines (MM001, MM011, MM031, MM057, MM074, MM087)." (PMID 35296667, 2022). "Nevertheless, a recent screening of hypermethylated genes in melanoma identified SOX10 to be methylated and consequently silenced in a subset of these tumors, thus demonstrating that SOX10 expression may be regulated by gene methylation in melanoma." (PMID 36040798, 2022). "Thus, SOX10 dictates fundamental gene expression programs in melanoma cases." (PMID 36224606, 2022). "Importantly, NECTIN4 was expressed in melanomas and co-expressed with SOX10." (PMID 33478111, 2021). "Intriguingly, downregulation of SOX10 expression in tumor cells was associated with decreased SAMMSON expression, suggesting that PITX1 plays a crucial role as a regulatory factor to directly suppress melanoma growth thorough the SOX9-SOX10 and SAMMSON pathway." (PMID 34526609, 2021). "Moreover, in melanoma cells, Sox10 ablation suppresses melanoma progression." (PMID 33803640, 2021). "Therefore, deciphering the transcriptional regulation of sox10 may reveal earlier mechanisms of melanoma initiation that drive NCP activation." (PMID 34099848, 2021). "Triple SOX10/SOX11/MITF positivity might serve as a diagnostic tool for conventional pan-melanoma cocktail negative cases." (PMID 33801642, 2021). "Importantly, unlike crestin, sox10 is conserved across all vertebrate species; therefore, identifying sox10 enhancers that are active in melanoma in zebrafish could more readily lead to the identification of human SOX10 enhancers that influence melanoma onset." (PMID 34099848, 2021). "Together, these data expand our understanding of transcriptional regulatory changes that control aspects of neural crest programs during normal development and in melanoma, and suggest a model wherein auto-regulation of sox10 in a feed-forward loop may contribute to the formation of melanoma." (PMID 34099848, 2021). "Therefore, we aim to identify neural crest regulatory elements that not only serve as a marker of melanoma, such as crestin, but also regulate sox10, which is conserved across species, to understand the foundations of transcriptional control of genes contributing to melanoma initiation." (PMID 34099848, 2021). "In addition, SOX10 appears to be binding a number of interesting genes in B16 melanoma as shown in the top enriched GO category regulating transcription as well as the other TFs that SOX10 binds nearby in cells, which could be playing a role in the transition." (PMID 32620903, 2020). "Indeed, we have also observed that inhibiting GSK3α/β in melanoma cell lines carrying a classical exon-3 mutation (β-catenin p.S37F) in the GSK3α/β consensus site did not have any effect on SOX10 protein levels." (PMID 32238882, 2020). "Additionally, SAMMSON expression in melanoma cells is promoted by the SOX10 transcription factor." (PMID 33329688, 2020).